CD59 (CD59 molecule (CD59 blood group))
Diseases named in the same sentence as CD59 in open-access papers (continued):
Sharing a sentence is not in itself a finding about the gene and the disease.
acute coronary syndrome (1 paper, 2024). Signs and symptoms related to acute ischemia of the myocardium secondary to coronary artery disease. "The role of the complement inhibitory proteins CD46 and CD59 in the immune response to an acute coronary syndrome (ACS) is unknown." (PMID 39523332, 2024).
acute leukemia (1 paper, 2026). A clonal (malignant) hematopoietic disorder with an acute onset, affecting the bone marrow and the peripheral blood. "The current study aims to assess post-transcriptional expression levels of complement regulatory proteins CD35 and CD59 in acute leukemia patients." (PMID 41925790, 2026). "CD35 expression was significantly downregulated in acute leukemia in comparison to their normal counterparts at both transcriptional and protein levels (5.3-and 4-folds respectively), conversely CD59 expression was significantly increased (3 and 1.3 folds respectively)." (PMID 41925790, 2026). "An HSB-2 acute leukemia cell model was established, and post-transcriptional silencing of CD35 and CD59 using shRNA was performed." (PMID 41925790, 2026).
acute pancreatitis (1 paper, 2017). An acute inflammatory process that leads to necrosis of the pancreatic parenchyma. "IL-4 reduced necrosis in this model of acute pancreatitis and authors suggested that this effect was related to enhanced expression of complement regulatory proteins, CD55 and CD59." (PMID 28665321, 2017).
adenoma (1 paper, 1993). A neoplasm arising from the epithelium. "In 20 colorectal normal mucosa samples, in ten adenomas, 71 carcinomas and in ten liver metastases derived thereof, CD59 was inconsistently expressed in the epithelial compartment." (PMID 7692919, 1993).
Allergy (1 paper, 2021). An allergy is an immune response or reaction to substances that are usually not harmful. "CD59 can be an infection‐ or allergy‐associated biomarker or therapeutic target for drug development." (PMID 34841705, 2021).
Anxiety (1 paper, 2025). Intense feelings of nervousness, tension, or panic often arise in response to interpersonal stresses. "Given the high prevalence of anxiety disorders as an additional comorbidity in CD59, future studies should extend this approach to include anxiety in order to develop a more comprehensive model of neuropsychological involvement in inflammatory bowel disease." (PMID 40962841, 2025).
anxiety disorder (1 paper, 2025). A category of psychiatric disorders which are characterized by anxious feelings or fear often accompanied by physical symptoms associated with anxiety. "Another relevant consideration is the frequent comorbidity of anxiety disorders in individuals with CD59." (PMID 40962841, 2025).
Autoimmunity (1 paper, 2019). The occurrence of an immune reaction against the organism's own cells or tissues. "One such protein of interest is the CD59 glycoprotein that limits damage caused by the activation of the immune system and autoimmunity." (PMID 31133884, 2019).
bone marrow failure syndrome (1 paper, 2021). "Occasionally, CD55 and/or CD59 deficient clones are detected in non-cytopenic patients and patients with no apparent bone marrow failure syndromes and in about 4,1% in healthy volunteers (1.6, 0.8% and 1,6% with CD55−/CD59-, CD55−/CD59+, and CD55+/CD59- cells respectively)." (PMID 33691713, 2021).
brain infarction (1 paper, 2018). Tissue necrosis in any area of the brain, including the cerebral hemispheres, the cerebellum, and the brain stem. "Mutations in CD59 result in recurrent brain infarctions and absent protein expression on brain endothelial cells." (PMID 29740431, 2018).
Budd-Chiari syndrome (1 paper, 2025). "Flow cytometry using FLAER (Fluorescent AERolysin) and CD55/CD59 confirmed large PNH clones in granulocytes and monocytes, consistent with classic PNH complicated by hepatic vein thrombosis, Budd-Chiari syndrome (BCS)." (PMID 41450399, 2025).
Cachexia (1 paper, 2021). Severe weight loss, wasting of muscle, loss of appetite, and general debility related to a chronic disease. "Similarly, human hepatocytes are characterized by high expression of a battery of complement inhibitors, including CD46, CD55, CD59, and factor H, although it is not known whether their expression is stable in metabolic disorders such as obesity or cachexia." (PMID 34830921, 2021).
cardiomyopathy (1 paper, 2017). A disease of the heart muscle or myocardium proper. "We identified genes with alternative splicing profiles that were common to cardiomyopathy (PDLIM3, CD36, CLDND1, TTN, FAM126a, TLR4, and CD59)." (PMID 28098235, 2017).
Cerebral ischemia (1 paper, 2010). Restriction of arterial blood supply to the brain associated with insufficient oxygenation to support the metabolic requirements of the tissue. "In a mild model of cerebral ischemia with selective neuronal cell death, CD59 leads to less neuronal dysfunction and a smaller infarct volume." (PMID 20202211, 2010). "Based on the data, we conclude that the complement inhibitor protein CD59 is protective after cerebral ischemia in a gender specific way, and that this effect depends on the severity of the cerebral damage." (PMID 20202211, 2010).
cervical intraepithelial neoplasia (1 paper, 2022). "To determine the clinical relevance of the NANOG-CD59 axis in human cancer, we evaluated the CD59 level by immunohistochemistry in cervical tissue specimens from patients with cervical intraepithelial neoplasia (CIN) and further analyzed their relationship with the previously reported NANOG19." (PMID 35606403, 2022).
chronic hepatitis B (1 paper, 2020). "In chronic hepatitis B patients, HBV sensitizes hepatocytes to complement-mediated killing through down-regulation of the complement-regulating membrane protein CD59, causing liver inflammation, and clearing the virus." (PMID 33643280, 2020).
Cirrhosis (1 paper, 2017). A chronic disorder of the liver in which liver tissue becomes scarred and is partially replaced by regenerative nodules and fibrotic tissue resulting in loss of liver function. "Specifically, by using ascites from small patient groups with HGSOC or cirrhosis and a small set of cancer-associated proteins, we observed that EV-associated MMP9 in HGSOC is predominantly localized in AV-binding EVs and that both CD59 and MMP9 in AV-binding EVs are candidate biomarkers for HGSOC." (PMID 28607529, 2017).
coeliac disease (1 paper, 2016). "CD59 is upregulated in patients with gastritis, coeliac disease and inflammatory bowel disease." (PMID 27215188, 2016).
Cognitive impairment (1 paper, 2020). Abnormal cognition is characterized by deficits in thinking, reasoning, or remembering. "Furthermore, carriers in the moderate cognitive impairment stage showed lower levels than controls of complement C1q subcomponent subunit-B [C1QB] and CD59, which was also observed in the replication cohort." (PMID 32460813, 2020).
cortical dysplasia (1 paper, 2017). "The assessment of protein expression of a wide range of markers showed that the two patients with cortical dysplasia, included in this study, express higher percentages of several neuroblast and stem cell markers including DCX, NeuN, Nurr1, CD56, CD166, CD9, CD73, CD59, CD61 and cKit." (PMID 28796246, 2017).
demyelinating polyneuropathy (1 paper, 2019). Polyneuropathy that is characterized by demyelination of axons. "Recently, a homozygous frameshift deletion in CD59 (c.146delA, pAsp49Valfs*31) has been described in a 7-year-old girl with a demyelinating polyneuropathy and cerebral vasculopathy." (PMID 30794663, 2019).
demyelination (1 paper, 2023). "However, only CD59-deficient patients, and not CD55-deficient patients, are under frequent PNS attack leading to recurrent PNS demyelination episodes and conduction block, indicating the crucial role of CD59 in protecting myelin from complement attack." (PMID 37875972, 2023).
depression (1 paper, 2021). "However, findings for the postpartum samples showed only a trend of association between the expressions of CAT, CD59, and RAPH1 blood markers and depression scores." (PMID 33479202, 2021).
developmental delay (1 paper, 2018). "Furthermore, the cell surface levels of CD55 and CD59 were on average lower in cells that were derived from individuals with mutations in PGAP3 compared to individuals with mutations in PIGV, although this did not correspond to a higher prevalence of seizures or a more severe developmental delay." (PMID 29310717, 2018).
diabetic nephropathy (1 paper, 2013). "CD59 concentration in the urine of patients with membranous glomerulonephritis was higher in comparison to urinary CD59 from healthy controls and patients with diabetic nephropathy." (PMID 24327929, 2013).
disc degeneration (1 paper, 2021). "Despite the differences observed in IVD tissues from disc degeneration compared to AIS patients, namely, increased TCC deposition and expression of CD59 (a direct TCC inhibitor), the expanded AF cells from both patient groups revealed similar behavior." (PMID 35155408, 2021).
Duchenne muscular dystrophy (1 paper, 2017). Duchenne muscular dystrophy (DMD) is a neuromuscular disease characterized by rapidly progressive muscle weakness and wasting due to degeneration of skeletal, smooth and cardiac muscle. "CD29+, CD44+, CD59+, and CD90+ cells from menstrual blood are capable of differentiating into myoblasts/myocytes and conferring human dystrophin expression in the murine model for Duchenne muscular dystrophy." (PMID 28706537, 2017).
Erythema (1 paper, 2023). Redness of the skin, caused by hyperemia of the capillaries in the lower layers of the skin. "TCE- and CD59-group mice were divided into a sensitization-positive group (erythema or edema) and a sensitization-negative group (no reaction) according to the dorsal skin reaction." (PMID 37383224, 2023).
esophageal cancer (1 paper, 2018). A primary or metastatic malignant neoplasm involving the esophagus. "We examined the relationship between CD59 expression and radioresistance and investigated the influence of CD59 deficiency on the radiosensitivity of esophageal cancer cell lines using various in vitro and in vivo assays." (PMID 30166523, 2018). "In this study, we found that the expression level of CD59 was positively correlated with the radioresistance of esophageal cancer cell lines and clinical specimens." (PMID 30166523, 2018). "Genetic alteration of CD59 expression modulated the radiosensitivity of esophageal cancer cells to ionizing radiation." (PMID 30166523, 2018). "This study showed the complement-independent role of CD59 and revealed novel therapeutic opportunities for improving the radiation response of esophageal cancer." (PMID 30166523, 2018). "In addition, the MAC displayed an extensive and similar staining in tumor tissues derived from control and CD59-KO esophageal cancer cells, which further supports the complement-independent role of CD59 in modulating radiosensitivity." (PMID 30166523, 2018). "However, the effect of CD59 on the esophageal cancer response to ionizing radiation remains unclear." (PMID 30166523, 2018).
geographic atrophy (1 paper, 2023). "A decrease in CD59 labeling was found in the geographic atrophy area." (PMID 37366063, 2023).
Glucose intolerance (1 paper, 2024). Glucose intolerance (GI) can be defined as dysglycemia that comprises both prediabetes and diabetes. "Plasma glycated CD59, detectable via a sensitive and specific enzyme-linked immunosorbent assay, has been suggested as a promising diagnostic and predictive biomarker of type 2 diabetes, pregnancy-induced glucose intolerance, gestational diabetes, and postpartum glucose intolerance." (PMID 39518935, 2024).
Guillain-Barre syndrome (1 paper, 2023). A spectrum of rare post-infectious neuropathies that usually occur in otherwise healthy patients. "This renders the nodes and myelin in the PNS vulnerable to complement attack and demyelination in autoinflammatory Guillain-Barré syndrome, as seen in CD59 deficiency." (PMID 37875972, 2023).
herpesvirus infection (1 paper, 2025). "Another well documented Ly6/uPAR protein, CD59, is shown to involve KSHV and other herpesvirus infection." (PMID 40373067, 2025).
IgA nephropathy (1 paper, 2018). "Moreover, higher transcripts of CD46, CD55, CD59, and CFI were observed in recurrent IgAN nephropathy than in native kidney IgA nephropathy." (PMID 30356754, 2018).
invasive breast carcinoma (1 paper, 2016). A carcinoma that infiltrates the breast parenchyma. "On the other hand, CD59, a complement regulatory protein, decreases in invasive breast cancer." (PMID 27857940, 2016).
liver cirrhosis (1 paper, 2005). "The amount of cell-free CD59 was found to be higher in AF than in sera and in AF from patients with liver cirrhosis." (PMID 15726105, 2005).
lupus nephritis (1 paper, 2024). Glomerulonephritis in the context of systemic lupus erythematosus. "This study highlights the importance of looking at the balance between complement activation (e.g., MAC complex) and regulation (e.g. CD 59) in evaluating complement biomarkers and suggests C3, CFI and C9-to-CD59 ratio may be a marker of tubulointerstitial disease in lupus nephritis." (PMID 38895123, 2024). "We found that lupus nephritis patients with moderate to severe IFTA have increased urinary C3, CFI, and C9-to-CD59 ratio as compared to those with none to mild IFTA." (PMID 38895123, 2024).
lymph node metastasis (1 paper, 2022). "Higher EV CD59 levels were significantly correlated with distant metastasis (p = 0.0475), and higher EV TSPAN9 levels were significantly associated with lymph node metastasis (p = 0.0011), distant metastasis at diagnosis (p = 0.0104) and higher TNM stage (p = 0.0065)." (PMID 36612172, 2022). "Finally, we explored the potential association of plasma-derived EV levels of ADAM10, CD59, TSPAN9 and plasma CEA with different clinicopathological characteristics, including gender, age, TNM stage, tumor stage, lymph node metastasis and distant metastasis, of enrolled CRC patients." (PMID 36612172, 2022).
membranous glomerulonephritis (1 paper, 2013). A slowly progressive inflammation of the glomeruli characterized by immune complex deposits at the glomerular basement membrane, resulting in a thickened membrane, and nephrotic syndrome. "When the CD59 immunofluorescent expression in renal tissue samples from patients diagnosed with membranous glomerulonephritis was compared to that in healthy controls, membranous glomerulonephritis patients had lower CD59 expression." (PMID 24327929, 2013).
meningioma (1 paper, 2018). A generally slow growing tumor attached to the dura mater. "While C1QA complement component has not been intensely studied in meningioma, different levels of complement regulatory membrane proteins, particularly CD55 and CD59, have been reported in meningioma by several groups." (PMID 29662628, 2018).
meningitis (1 paper, 2006). A disorder characterized by acute inflammation of the meninges of the brain and/or spinal cord. "In this study, we assessed the capacity of brain epithelial cells to express membrane-bound complement regulators (ie, CD35, CD46, CD55 and CD59) in vitro and in situ by immunostaining of control and meningitis human brain tissue sections." (PMID 16948860, 2006). "Ependymal cells express CD55, CD59 and CD46 antigens in normal cases and the stainings were increased in meningitis cases." (PMID 16948860, 2006).
meningococcal meningitis (1 paper, 2021). "Additionally, levels of several complement regulators (CD35, CD46, CD55 and CD59) were shown in the CP of patients who suffered from meningococcal meningitis." (PMID 34425919, 2021).
myocardial inflammation (1 paper, 2024). "We hypothesize that both CD46 and CD59 shedding and the potent cytokine and chemokine release into the circulation are simultaneously involved in the acute phase of the post-ischemic immune response and myocardial inflammation." (PMID 39523332, 2024).
myositis (1 paper, 2017). "Perhaps the myositis seen in a very small number of NMO patients is caused by altered CD59 expression or CD59 polymorphisms, though this possibility has not been investigated." (PMID 28750658, 2017).
nephritis (1 paper, 2012). Inflammation of renal tissue. "We also observed a decreased CD35 and CD59 expression on RBCs from SLE patients with nephritis (n = 45) (P < 0.05, data not shown)." (PMID 22761633, 2012).
osteoporosis (1 paper, 2025). A condition of reduced bone mass, with decreased cortical thickness and a decrease in the number and size of the trabeculae of cancellous bone (but normal chemical composition), resulting in increased fracture incidence. "PTH and CD59 were significantly upregulated in all kinds of parathyroid subpopulation in osteoporosis patients." (PMID 40496565, 2025). "GO and KEGG enrichment revealed PTH, NOTCH, FGF, EGF and CD59 pathways were significantly up-regulated in all parathyroid subpopulations in osteoporosis patients." (PMID 40496565, 2025). "CD59 was also upregulated in in each subpopulation of osteoporosis cells." (PMID 40496565, 2025).
Pancytopenia (1 paper, 2018). An abnormal reduction in numbers of all blood cell types (red blood cells, white blood cells, and platelets). "At that time, the patient had pancytopenia and 5.4% of RBCs were CD59 deficient." (PMID 30116241, 2018).
periodontitis (1 paper, 2019). An acute or chronic inflammatory process that affects the tissues that surround and support the teeth. "An immunohistochemical study showed that the complement regulator CD59 is expressed at lower levels in the gingiva of periodontitis patients as compared to healthy individuals, which might imply compromised protection of periodontitis-involved tissues against MAC-mediated autologous tissue damage." (PMID 30915073, 2019).
Pleural effusion (1 paper, 2023). The presence of an excessive amount of fluid in the pleural cavity. "The expression levels of soluble CD46 (sCD46), soluble CD55 (sCD55), and soluble CD59 (sCD59) in pleural effusion were quantified by enzyme-linked immunosorbent assay, and the receiver operating characteristic (ROC) curves were plotted to evaluate the diagnostic and co-diagnostic values." (PMID 36820087, 2023).
Protein-losing enteropathy (1 paper, 2020). Abnormal loss of protein from the digestive tract related to excessive leakage of plasma proteins into the lumen of the gastrointestinal tract. "Isolated congenital CD55 deficiency is rare but has been observed in patients suffering from severe early-onset protein-losing enteropathy, whereas severe Guillain-Barré-like neurological symptoms with hemolysis are the hallmark of isolated CD59 deficiency." (PMID 32064578, 2020).
psoriasis (1 paper, 2024). An autoimmune condition characterized by red, well-delineated plaques with silvery scales that are usually on the extensor surfaces and scalp. "In a mouse psoriasis model, topical application of MSC-EVs suppresses C5b9 complement complex through CD59 and reduces IL-17 secreted by neutrophils, thereby alleviating psoriatic skin inflammation." (PMID 39698413, 2024).
renal clear cell carcinoma (1 paper, 2021). "The authors found that expression of CD55 and CD59 is increased in renal clear cell carcinoma, which may contribute to the progression of these tumors." (PMID 34572075, 2021). "The histological findings of C3d and C5b-9 on renal tumor cells led to the hypothesis that the complement system could be involved in the immune response against ccRCC expression level and cellular distribution of CD46, CD55, and CD59 on renal clear cell carcinoma cells." (PMID 34572075, 2021).
retinal detachment (1 paper, 2011). An eye emergency condition which may lead to blindness if left untreated. "Previous studies in mice in which membrane-targeting murine or rat CD59 have been injected into the vitreous did not include an approach to detect retinal detachment occurring during the intravitreal injection and hence unintended access to the subretinal space may have occurred." (PMID 21552568, 2011).